CD4 (CD4 molecule)
Diseases named in the same sentence as CD4 in open-access papers (continued):
Sharing a sentence is not in itself a finding about the gene and the disease.
Autoimmunity (continued). "The most plausible mechanism that could explain the role of infections in the triggering of autoimmunity is molecular mimicry, which consists of a cross-reaction between self and nonself epitopes, leading to their presentation by antigen-presenting cells to autoreactive CD4+ T cells." (PMID 37374092, 2023). "The tolerogenic capacity of CD4+CD25+FOXP3+ regulatory T cells (Tregs), have been extensively studied in the context of transplant rejection, autoimmunity, and cancer." (PMID 37868962, 2023). "The abundance of Desulfovibrio piger is associated with a higher level of plasma 1-arachidonoyl-GPC, a metabolite known to negatively affect CD4+, CXCR3+, CD8+, and CXCR3+ T cells, preventing further progression of autoimmunity." (PMID 36341463, 2022). "We also assayed differentiation of the two Treg‐P populations, CD25+FOXP3− (CD25+) Treg‐P and CD4+CD25−FOXP3lo (FOXP3lo) Treg‐P, as these two subsets differ in their developmental programs and capacity to prevent autoimmunity." (PMID 35561351, 2022). "CD4+CD45RA+CD25+Foxp3+CD127loTreg are resting thymus-derived cells, known as either nTreg or tTreg that prevent autoimmunity." (PMID 36426347, 2022). "CD4+FOXP3+ Tregs are T-cells with immune suppressive activity that typically mediate peripheral tolerance and prevents autoimmunity." (PMID 35158816, 2022). "Within human chronic kidney disease, CCR6−CXCR3−CXCR5+PD-1+CD4 and exhausted CD8 T cells are upregulated compared to end-stage kidney disease showcasing exhausted populations in CD4 and CD8 T cells during autoimmunity." (PMID 36314014, 2022). "Enumeration of early differentiation stages of CD4+ and CD8+ T cells defined by co-expression of CD27/28 molecules revealed reduced numbers in autoimmune cytopenia and organ specific autoimmunity subgroups of patients with CVID." (PMID 35795667, 2022). "Recent literature suggests that certain pathogenic Th17 cell subsets with Th1 characteristics, such as CD4+CD161+CCR6+CXCR3+IL-17+IFN-y+ (Th17.1) and CD4+CD161+CCR6+CXCR3+IL-17-IFN-y+ (exTh17), are important contributors in Th1-mediated autoimmunity." (PMID 35967358, 2022). "CD4+CD25+Foxp3+ Treg are essential for maintaining immune homeostasis, preventing autoimmunity, and promoting tolerance." (PMID 35493508, 2022). "Reduced frequency of CD4+CD25HIGHFOXP3+ cells and diminished FOXP3 expression in patients with Common Variable Immunodeficiency:A link to autoimmunity?" (PMID 35795667, 2022). "In earlier studies, we showed that these FoxP3+ T cells (both CD4+ and CD8+ Treg) suppressed autoimmunity in vivo and anti-DNA production in vitro." (PMID 34093553, 2021). "During the evolution of viral pneumonia, the balance of T cells, CD4 T cells, and CD8 T cells is crucial in the fight against pathogens and the development of autoimmunity." (PMID 34451520, 2021). "Numerous lines of evidence indicate that multiple sclerosis (MS) is driven by CD4 + T cells, and EAE is a classic model of CD4+ T cell-mediated autoimmunity." (PMID 33692790, 2021). "We have shown that Tregs not only inhibit the generation of anti-MPO autoimmunity, but that they also suppress established responses of MPO-specific CD4 T cells, CD8 T cells and B cells." (PMID 34394071, 2021). "Our results showed higher sharing of TCRVβ sequences between CD4+ TEM and CD8+ TCM cells in WAS chimeric mice than in WT, suggesting that WAS chimeric mice are more prone to autoimmunity than WT." (PMID 35116029, 2021). "Our findings indicate that DRD3-expression in CD4+ T cells was irrelevant in EAE, whilst DRD3 in B cells exerted fundamental regulatory processes in CNS autoimmunity." (PMID 34920747, 2021). "DCs prevent tissue-destructive autoimmunity after heart injury by activating conventional fork-head box protein P3 (FOXP3)– CD4 + T helper cells and FOXP3 + CD4 + Treg cells." (PMID 33612829, 2021).
Autoimmunity (continued). "We found that this heritability was significantly enriched in cell type specific accessible chromatin as measured by ATAC-seq in CD4+ T-cells, CD8+ T-cells, and B-cells reflecting the contribution of immune cells involved in autoimmunity." (PMID 34099659, 2021). "To assess the ability of iTregs to suppress T‐cell responses in vivo, we used a T‐cell model of autoimmunity, experimental autoimmune encephalomyelitis (EAE), in which Th17 CD4+ cells play a critical role in driving disease pathology through IL‐17 secretion." (PMID 33988885, 2021). "Characterising CD4 TCR clonality has been used to monitor progression of disease states in cases of infection and autoimmunity, including RA." (PMID 33986757, 2021). "T-cells, including CD4+ cells, and CD8+ cells play an antiviral role not only by combating against virions but also restricting the development of autoimmunity or overwhelming inflammation." (PMID 32344708, 2020). "Nevertheless, CD4+ and CD8+ T cells are thought to be the primary drivers of β cell autoimmunity in most cases of human T1D." (PMID 33603744, 2020). "Activated and developing central memory CD4 and CD8 T cells were found in PL disease similar to C57BL/6 mice that develop autoimmunity with delayed kinetics." (PMID 33319815, 2020). "Similarly, we also observed an increase in HLA-DR expression along with co-stimulatory molecules CD80 and CD86 in stimulated pDCs, suggesting that pDCs can efficiently present antigens to CD4 + T cells during autoimmunity and may contribute to the pathogenesis of T1D." (PMID 32483133, 2020). "As CD4+ T cell subsets, T helper 17 (Th17) cells and Th1 cells produce IL-17 and IFN-γ, respectively, to mediate inflammation and autoimmunity." (PMID 32075652, 2020). "The current mini review focuses on exploring the role of CXCR3 ligands in directing the biological properties of CD4+ and CD8+ T cells in the context of cancer and autoimmunity." (PMID 32547545, 2020). "Dysregulated functions associated to immunosenescence can include reduced responses to vaccination, lower antitumor ability of CD4, CD8 T cells and APC, increased systemic inflammation, as well as autoimmunity." (PMID 33162990, 2020). "Compared with APP+/+ mESC-TEP-transplanted mice, the percentage of IFNγ-producing CD4 T cells in APP−/− mESC-TEP-transplanted mice showed a larger increase, which is probably due to enhanced anti-Aβ autoimmunity in APP−/− mESC-TEP-transplanted AD mice." (PMID 32849642, 2020). "We have also previously observed that Egr2−/− MP CD4 T cells in old CD2- Egr2−/− mice, which are also prone to develop autoimmunity, have increased homeostatic proliferation." (PMID 32709717, 2020). "Furthermore, nT1D participants presented considerably lower CD69+ CD4+ activation response compared to HC, indicating the potential effect of the immune exhaustion and tolerance as the result of previous exposure to miRNAs involved in the development of T1D autoimmunity and beta-cell destruction." (PMID 32296701, 2020). "On the other hand, IL-21 influences B-cell function: IL-21 signaling in B cells is required, together with CD4− T cell cooperation, for their differentiation to antibody-producing plasma cells, that in turn could be important in the development of antibody-induced autoimmunity." (PMID 32503344, 2020). "While several studies have shown reduced CD4+ cells in CVID, those with autoimmune cytopenias and organ specific autoimmunity had the most significantly reduced CD4+ T cells." (PMID 31921101, 2019). "Furthermore, we noticed that despite the fact that Lin28Tg CD4+ T cells have enhanced potentials for differentiation into pathogenic Th17 cells, Lin28Tg mice are healthy and do not demonstrate signs of autoimmunity, suggesting unaltered Treg function in the absence of let-7 miRNAs." (PMID 32010153, 2019).
Autoimmunity (continued). "Here the authors show, in a mouse model of autoimmune encephalomyelitis, that memory-like CD4 T cells expressing unrelated TCR can also infiltrate the spinal cord and contribute to autoimmunity." (PMID 30755603, 2019). "CD4+CD25+FoxP3+ Tregs are highly involved in the regulation of immune responses and preventing autoimmunity." (PMID 30093899, 2018). "Additional cell adhesion molecules such as activated leukocyte cell adhesion molecule (ALCAM) and melanoma cell adhesion molecule (MCAM) also control transmigration of the CD4+ and CD8+ T cells across the BBB and CNS autoimmunity." (PMID 29411111, 2018). "On the other hand, the CD4+ CD25+ Foxp3+ Treg cells, as protective factors in the autoimmunity and tissue damaging process, are also targets for various therapeutic treatments." (PMID 28198408, 2017). "Another study described that autoimmunity can be also induced by antigen-specific CD8+T cells in the model of uveitis, albeit CD4+T cell-driven disease being dominant." (PMID 29068389, 2017). "Our results indicate that CD4+CD28null T cells expand after repeated immune activation, either as a result of CMV infection or after the induction of autoimmunity." (PMID 28386103, 2017). "Since regulatory T cells (Treg) and the PD-1 pathway are critical in the development of autoimmunity including EAU36–38, we examined the expression of PD-1 and the Treg marker Foxp3 in HEL-specific CD4+ T cells after MCMV-HEL infection." (PMID 29079770, 2017). "Given the importance of autoreactive CD4+ T cells in initiating and perpetuating β-cell autoimmunity, we examined whether there are distinct, disease-associated features of the T cell receptor (TCR) in this setting, which could increase the risk of autoimmunity." (PMID 29176645, 2017). "IL-4 promotes the differentiation of CD4 T cells toward the Th2 phenotype, and IL-10 and TGF-β are known to exert anti-inflammatory activity and to suppress autoimmunity through mechanisms that include the induction of Treg44." (PMID 28851867, 2017). "Which CD4 T cells subsets, e.g., Th17 or Th-GMCSF cells, are relevant for the induction of autoimmunity in the eye, and how do they dynamically interact with the retina and with antigen presenting cells?" (PMID 28066446, 2016). "The importance of CTLA-4 in regulating autoimmunity was demonstrated early on in CTLA-4 knockout mice, in which CD4-predominant lymphoproliferation develops and results in T cell infiltration of multiple organs and early mortality at 3–4 weeks." (PMID 28031819, 2016). "These are the first data to show a differential role of Foxp3+ Tregs versus Tr1 cells in limiting SR CD4+ T cells in CLN and CNS, respectively, thereby maximizing prevention of autoimmunity." (PMID 27708643, 2016). "Although many studies are focused on auto-reactive CD4+ T cells, the precise role of CD8+ T cells in autoimmunity is poorly understood." (PMID 27195110, 2016). "Finally, the implication of SR CD4+ T cells in promoting tissue damage and clinical autoimmunity during JHMV infection remain unclear, as increased myelin-specific CD4+ T cells in IL-27R−/− mice correlated with a moderate decrease, rather than expected increase in demyelination." (PMID 27708643, 2016). "Therefore, in addition to being critical in promoting Treg activity, TNFR2 signaling is also likely to play a role in the development of more pathogenic CD4 effector cells and consequently may contribute to the inflammatory pathogenesis of CD4 cell-mediated autoimmunity." (PMID 27601345, 2016). "Regulatory T cells (Tregs), defined as CD4+CD25+Foxp3+ or CD4+CD25+CD127low/−, mediate peripheral tolerance and prevent autoimmunity in healthy individuals." (PMID 27762298, 2016). "Given that the Th17 response is promoted in CFA-induced models of autoimmunity, PMA- and ionomycine-stimulated CD4+ dLN T lymphocytes were also examined for the frequency of IL-17+ cells." (PMID 27832210, 2016).
Autoimmunity (continued). "At active stage, the increase of TRAb levels and perivascular CD4+ and CD8+ T lymphocyte infiltration implied the activation of humoral and cell-mediated autoimmunity, which would result in excessive hyaluronan deposits and fibrous tissue hyperplasia." (PMID 27648339, 2016). "tDC expand CD4+ CD25+ Treg from CD4+ CD25− precursors, leading to the expansion of antigen-specific Treg which contribute to the prevention of autoimmunity." (PMID 25890330, 2015). "Regulatory T cells are T helper cells CD4+ which additionally demonstrate an expression of a reactor for IL-2 alpha chain (CD25) and are responsible for suppressing autoimmunization." (PMID 26000316, 2015). "As these mice possess both CD8+ and CD4+ myelin-reactive T cells, we can address both the role of CD8+ T cells in CNS autoimmunity and the pathophysiology of progressive MS." (PMID 26557120, 2015). "The human immune system has a natural autoimmunity towards HSP, particularly HSP60 here, whereby CD4+ T-cells responses would be generated." (PMID 26146643, 2015). "Regulatory T cells (Tregs), specifically CD4+CD25+ and Forkhead box P3+ (FoxP3+) Tregs, acquired notable attention because of their role in a variety of autoimmune pathologies." (PMID 26788051, 2015). "Tregs, phenotyped as CD4+CD25+ cells, were shown to be important for self-tolerance in mice, as inoculation of CD4+ cells depleted of CD4+CD25+ cells resulted in autoimmunity in nude mice." (PMID 26500653, 2015). "Inducible CD4+CD25+Foxp3+ regulatory T cells (iTreg) develop outside of the thymus and play an essential role in controlling of chronic inflammation and autoimmunity." (PMID 25393765, 2014). "Dissimilarities included greater prevalence of autoimmune conditions, lower median IgG, IgA, and IgM, and lower median CD19+, CD3+/CD4+, and CD3+/CD8+ blood lymphocytes in CVID patients." (PMID 25295286, 2014). "Antigen-specific CD4+CD25+ T regulatory cells (Treg) mediate transplant tolerance and can protect against autoimmunity." (PMID 24847323, 2014). "The role of blood CXCR5+CD4+T cells in patients with autoimmunity has been explored, but little is known about the role of circulating CXCR5+CD4+ T cells in patients with chronic HBV infection." (PMID 24655429, 2014). "Dissimilarities included greater prevalence of autoimmune conditions, and lower median serum IgG, IgA, and IgM levels and lower median levels of CD19+, CD3+/CD4+, and CD3+/CD8+ blood lymphocytes in CVID patients." (PMID 25295286, 2014). "The strongest genetic link with autoimmunity is to major histocompatibility (MHC) class II genes, implicating CD4 T cells in autoimmune pathogenesis." (PMID 24782861, 2014). "Later, activated CD4+ T cell in normal animals that expressed CD25 and prevented autoimmunity in neonatal thymectomized mice were described." (PMID 23935597, 2013). "Immune regulation by CD4+CD25+FoxP3+ regulatory T-cells (Tregs) and 17β-estradiol is crucial in the pathogenesis of sex bias in cancer and autoimmunity." (PMID 23577207, 2013). "Only a small percentage of CD4+ T cells coexpresses NKG2D, but these cells correlate with disease in different autoimmune disorders." (PMID 24282598, 2013). "In CVID, low proportions of CD4 + CD25+, Foxp3 T regulatory cell subset correlated with presence of autoimmunity and splenomegaly." (PMID 24044622, 2013). "In the tonsils of IgAN patients, CD4+/CD25+ cells have been reported to be reduced, as in patients with PFAPA; local abnormalities of autoimmunity in the tonsils have also been suggested." (PMID 22940910, 2013). "The interaction between MHC II-peptides and TCRs constitutes the molecular base for all CD4 T cell-mediated immune responses and the displayed MHC II peptidome is critical to the generation of tolerance, immunity, and autoimmunity." (PMID 24379811, 2013).
Autoimmunity (continued). "It is generally accepted that a decrease of the peripheral T-cell repertoire with a particular emphasis on the CD4+/CD8+ T-cell ratio affects the balance between regulatory and effector cells and thus triggers mechanisms of autoimmunity." (PMID 23717591, 2013). "IL-23R plays a key role in the differentiation of CD4 T-cell into TH17 lymphocytes, which mediate inflammations in several animal models of autoimmunity." (PMID 23767933, 2013). "Thus, removal of TR2 from mature CD4+ T cells does not result in tolerance loss or autoimmunity." (PMID 24115907, 2013). "CD4+ CD25+ forkhead box P3 (FoxP3)+ regulatory T cells (T reg cells) are known to suppress adaptive immune responses, key control tolerance and autoimmunity." (PMID 22373353, 2012). "These autoimmune disorders are prevented by reconstituting the mice with CD4+CD25+ Treg cells, indicating a therapeutic potential for Tregs for the treatment of autoimmunity." (PMID 22876242, 2012). "CD4+CD25+ Treg cells are of paramount importance in the maintenance of peripheral self-tolerance and avoidance of autoimmunity." (PMID 23116248, 2012). "Mutations in the FOXP3 gene (located on the centromeric region of the X chromosome) lead to decreased CD4 + CD25+ Tregs, and therefore failure to suppress the production of autoreactive T cells and multi-organ autoimmunity." (PMID 22816667, 2012). "In contrast to Th17 cells, CD4+CD25+ and FOXP3+ (Tregs) play a critical role in maintaining self-tolerance and in preventing organ-specific autoimmunity, allergy, and allograft rejection." (PMID 23345934, 2012). "Infusion of donor CD4+CD25+ Tregs, which are critical for maintenance of self-tolerance and prevention of autoimmunity, has been found to effectively inhibit GVHD." (PMID 23077554, 2012). "Autoreactive T-cell clones can downregulate CD4 upon long-term stimulation in vitro, and self-specific TCR-transgenic mice can downregulate coreceptors to control autoimmunity." (PMID 21749708, 2011). "The regulation of Th17 cells is basically mediated by CD4+CD25+FoxP3+ T reg cells which are capable of inducing anergy towards self- and alloantigens, thus playing an important role in autoimmunity." (PMID 21188205, 2010). "CD4+CD25+ regulatory T cells play an essential role in maintaining immune homeostasis and preventing autoimmunity." (PMID 19173720, 2009). "Foxp3, a 47-kDa transcription factor, is necessary for the function of CD4+CD25+ regulatory T cells (Tregs), with an essential role in the control of self-reactive T cells and in preventing autoimmunity." (PMID 19924293, 2009). "CD4+CD25+ regulatory T cells (Tregs) play a critical role in establishing immune tolerance and in prevention of autoimmunity." (PMID 19924293, 2009). "Here, we focus on the complex body of findings from viral, bacterial, and parasitic infection models, cancer and autoimmunity studies, as well as in vitro experiments using human and murine T cells, demonstrating that IFN-I can be directly sensed by CD4 T cells." (PMID 41897309, 2026). "These cells present the IL6-sIL6R complex to TH (CD4+) lymphocytes, which fix it upon the membrane gp130 and, secondary to transduction, transform into TH17 lymphocytes, secreting IL-17, with a strong pro-inflammatory role and favoring autoimmunity." (PMID 40283387, 2025). "The Th9 CD4+ subgroup is believed to originate from Th2 cells, after their “reprogramming” by TGF-β and IL-4, and has been shown to promote antitumor protection and prevent autoimmunity." (PMID 40589741, 2025). "In NMOSD, CD4 + T cell cultures have been correlated with EDSS scores, suggesting that Th cell-driven autoimmunity may amplify the disease process." (PMID 40933045, 2025). "Treg cells are a subset of CD4+ T helper cells characterized by the expression of the transcription factor Foxp3 and the surface receptor CD25 (IL-2 receptor alpha subunit) and are key for maintaining immune homeostasis and preventing autoimmunity." (PMID 41366167, 2025).